PON2 (paraoxonase 2)
Diseases named in the same sentence as PON2 in open-access papers (continued):
Sharing a sentence is not in itself a finding about the gene and the disease.
tumor (continued). "In urinary exfoliated cells from BC patients, PON2 mRNA levels showed an inverse correlation with tumor stage (pT)." (PMID 28430636, 2017). "The efficacy of this strategy is supported by results reported by previous studies demonstrating that PON2 knockdown induced apoptosis of several human tumor cell lines and enzyme overexpression increased chemotherapeutic resistance." (PMID 28430636, 2017). "The loss or inhibition of PON2 activates a starvation pathway, leading to AMPK activation, PUMA activation and anoikis and inhibition of tumor cell growth." (PMID 29156578, 2017). "The expression levels of PON2 in paired tumor and normal bladder tissue samples and in urinary exfoliated cells from patients affected with BC and healthy donors were evaluated." (PMID 28430636, 2017). "Our results showed that PON2 expression levels were significantly higher in BC compared with non-tumor tissue." (PMID 28430636, 2017). "To further investigate the mechanism of C12-triggered apoptosis, we studied the involvement of endogenous PON2 in C12 cytotoxicity in tumor cells." (PMID 26758417, 2016). "Overall, our study reveals that C12 inhibits tumor growth in animals as a single agent, through inducing a unique Bcl-2 protein-independent and PON2-mediated apoptotic cascade in tumors." (PMID 26758417, 2016). "Ex vivo analysis of OSCC patients revealed a correlation between PON2 and β-catenin expression in tumor tissue." (PMID 27322774, 2016). "Together with previous results, this verifies the tumor cell-stabilizing effect of PON2 and raises major interest in regulation of its expression." (PMID 27322774, 2016). "Furthermore, the interplay between PON2-mediated redox control, cell proliferation, and apoptosis in therapy-resistant tumours needs exploration to develop synergistic combination treatments that enhance oxidative stress or apoptotic signalling." (PMID 40794328, 2025). "Multi-omic strategies integrating genomics, transcriptomics, and metabolomics could provide deeper insights into how PON2 contributes to tumour heterogeneity, progression, and resistance to therapy." (PMID 40794328, 2025). "Moreover, PON2 silencing in Dex-resistant B-ALL cells led to reduced tumor growth following xenograft implantation in immunodeficient mice." (PMID 38397445, 2024). "The aims of this review were to provide an overview of the studies available in the scientific literature reporting altered PON2 expression in neoplasms, and to explore/reveal the involvement of enzymes in molecular mechanisms and cellular events featuring tumor cells." (PMID 38397445, 2024). "In addition, a significant inverse correlation was found between PON2 expression and tumor size, highlighting potential enzyme involvement in the early phases of oral tumorigenesis." (PMID 38397445, 2024). "Analysis of the identified candidates, along with previously published data on interactors obtained by other methods, indicates the presence of a significant number of indirect interactions between PON2 and EGFR and, consequently, possible regulation of tumor growth with mutant EGFR involving PON2." (PMID 36653584, 2023). "Furthermore, tumor growth in wild-type vs. PON2-KO animals was uniform, indicating that PON2 host status does not influence the subcutaneous growth of LLC cells." (PMID 37337025, 2023). "Conversely, a tumor suppressor role for PON2 was identified in the context of ovarian cancer." (PMID 37337025, 2023). "Given the heterogenicity of intrinsic (e.g., oncogenic profiles of neoplastic cells) and extrinsic properties (e.g., nutrient supply and oxygen availability) of the tumor niche, the effects of PON2 on tumorigenesis are likely vastly different among various cancer types." (PMID 37337025, 2023). "In wild-type animals, subcutaneous tumor growth was similar between control- and PON2-shRNA groups." (PMID 37337025, 2023).
tumor (continued). "Results showed that differential PON2 expression (tumor versus normal tissue) was significantly higher in subjects with relapse disease with respect to patients who experienced relapse-free survival, thus attributing to the enzyme an interesting predictive power of disease progression." (PMID 36613780, 2022). "The overexpression of PON2 in T24 cells treated with CSE could represent a mechanism by which tumor cells protect themselves from the apoptotic process induced by glucosinolates and polyphenols." (PMID 36235028, 2022). "Moreover, PON2 expression in BC patients’ urinary exfoliated cells was higher than in patients affected with tumours invading subepithelial connective tissue or extending outside the bladder (T1-T3)." (PMID 33923108, 2021). "The increase in PON2 expression was also found in tissue samples obtained from patients with gastric cancer, which had a significant positive correlation with the diffuse type, clinical stage, tumor invasion, lymph node metastases, and distant metastases." (PMID 34885171, 2021). "This could indicate that, especially in the early stages of tumor formation, the antioxidative and antiapoptotic function of PON2 and PON3 are beneficial as it helps to generate the platform for malignant transformation." (PMID 33562328, 2021). "There is only one study in which it is demonstrated that PON2 acts as a tumor suppressor." (PMID 33562328, 2021). "Moreover, C12 ability to kill NSCLC tumor cells in vitro (25–50 μM) and to block tumor growth in vivo mediated by PON2 is attributed to PON2 overexpression in tumors." (PMID 33562328, 2021). "Further studies are needed to address whether expression of OXR1 and PON2 may be involved in a mechanism by which this long-lived and thus vulnerable population of stem-like tumor cells protects itself against ROS-mediated damage." (PMID 33806447, 2021). "In this light, PON2 overexpression in BC could represent an adaptive mechanism of tumor cells to escape/survive cell death and apoptosis induced by chemotherapy." (PMID 32093309, 2020). "Due to its localization in the ER and mitochondria, PON2 could act as an antiapoptotic effect that can be of physiopathological relevance in tumor cells." (PMID 31191796, 2019). "In vitro studies have shown that the expression of the PON-2 protein regulates the Wnt/GSK3β/β-catenin pathway in multiple cell lines (K562, SCC-4, PCI-13); besides, a correlation between PON2 and β-catenin expression was observed in ex-vivo tumor tissue of oral squamous cell cancer (OSCC)." (PMID 31052559, 2019). "Elevated PON-2 levels may stabilize tumor cells by enhancing cellular stress resistance, attenuating mitochondrial ROS-mediated apoptosis." (PMID 31052559, 2019). "Further work needs to address the role of PON2 in an in vivo metastatic tumor model." (PMID 29531225, 2018). "Therefore, we evaluated the expression levels of PON2 in paired tumor and normal bladder tissue samples from patients affected with BC, most of which underwent radical cystectomy for treatment of advanced disease (pT3-4)." (PMID 28430636, 2017). "Moreover, PON2 overexpression in T24 cells led to a significant increase in tumor cell proliferation and resistance to oxidative stress." (PMID 28430636, 2017). "Interestingly, the parameter pT, which describes the size and extent of primary tumor, showed an inverse correlation with PON2 mRNA levels." (PMID 28430636, 2017). "Thus, the herein presented mechanistic insight contributes to a better understanding of tumor specific escape from cell death strategies and suggests PON2 as a new potential biomarker for therapy resistance or as a prognostic tumor marker." (PMID 27322774, 2016). "Since PON3 possesses overlapping enzymatic activities with PON2 to cleave C12, we investigated whether PON3 could functionally compensate for the loss of PON2 and re-sensitize tumor cells to C12." (PMID 26758417, 2016).
tumor (continued). "Moreover, if only patients were taken into consideration who received surgery-mediated tumor removal plus accompanying radiotherapy, PON2 levels remained significantly elevated in the relapse-experiencing group, while it was lower in patients without relapse." (PMID 27322774, 2016). "Moreover, C12's ability to kill NSCLC tumor cells in vitro and block tumor growth in vivo is mediated through PON2." (PMID 26758417, 2016). "Based on these findings, targeting PON2 in cancer cells either directly or indirectly through Wnt/β-catenin may contribute to restored death signaling in tumor cells." (PMID 27322774, 2016). "Furthermore, selective cytotoxicity of C12 on lung tumor cells and its inhibitory effects on tumor growth are likely related to upregulated PON2 expression in tumor cells." (PMID 26758417, 2016). "Intriguingly, PON2 as well as PON3 are frequently found upregulated in tumor samples." (PMID 22666600, 2012). "This could indicate that, especially in the early stages of tumor formation, the antioxidative and antiapoptotic function of PON2 and PON3 is important and beneficial as it helps generating the platform for malignant transformation." (PMID 22666600, 2012). "Therapeutic strategies aimed at reducing PON2 expression in tumor cells hold promise, as further understanding of the regulatory mechanisms governing PON2 upregulation may yield novel insights into carcinogenesis and facilitate the development of effective interventions." (PMID 40794328, 2025). "This review, focused exclusively on PON2, provides a general, complete, updated overview of the bulk of studies published in the last two decades describing how enzyme involvement in molecular processes and cellular events promotes malignant transformation and features tumor cell aggressiveness." (PMID 38397445, 2024). "The reported data demonstrated significantly different PON2 expression (tumor versus normal tissue) in patients who experienced disease relapse compared with those who had relapse-free survival, thus suggesting that the enzyme may have interesting predictive power for disease progression." (PMID 38397445, 2024). "Importantly, the frequencies of tumor-infiltrating myeloid subsets that include myeloid-derived suppressor cells (MDSCs) and tumor-associated macrophages were not impacted by PON2 expression in LLC tumor-bearing mice." (PMID 37337025, 2023). "In addition, a bioinformatic analysis of RNA and DNA sequencing data obtained from tumor samples taken from more than 10.000 patients with 31 different types of cancer indicated that a high level of PON-2 expression correlates with a worst prognosis in patients with multiple types of solid tumors." (PMID 31052559, 2019). "Interestingly, PON2 mRNA levels showed an inverse correlation with the clinical parameter pT, which takes into account the size and the extent of primary tumor, thus suggesting a potential role for the enzyme in the early stages of the tumor." (PMID 28430636, 2017). "Thus, if the opposite was true for PON2 overexpressing cells, this would ensure mitochondrial functionality and could support the energy efficacy of tumor cells." (PMID 22666600, 2012). "Functional assays show that PON2 silencing, particularly via shRNA or CRISPR-Cas9, reduces proliferation, induces apoptosis, and sensitises tumour cells to chemotherapeutic agents." (PMID 40794328, 2025). "PON2 also promotes colony formation and metastasis in PDAC, and its knockdown slows the growth of tumours by triggering apoptotic pathways." (PMID 40794328, 2025). "PON2, a membrane-bound enzyme with antioxidant properties, is overexpressed in HNSCC tissues and has been shown to promote tumor cell survival by mitigating mitochondrial ROS production and preventing apoptosis." (PMID 40427390, 2025).
tumor (continued). "In order to determine the enzyme’s biological role in GC cells, PON2 silencing was performed in the MKN45 and SGC-7901 GC cell lines, and the effects on tumor cell phenotype were investigated." (PMID 38397445, 2024). "The mouse ID8 OC cell line, which overexpresses PON2, and control cells were subcutaneously injected into the flanks of C57BL/6J nude mice, and tumor formation was monitored." (PMID 38397445, 2024). "Researchers also investigated PON2’s role in pancreatic ductal adenocarcinoma (PDAC) tumor growth and metastasis using multiple murine tumor models." (PMID 37337025, 2023). "Therefore, it is reasonable to hypothesize that PON2 upregulation featuring cancer could represent a strategy adopted by tumor cell to escape the effects induced by chemotherapeutic drugs, especially those whose mechanism of action is mediated by oxidative stress induction." (PMID 36613780, 2022). "In this study, we focused our attention on the enzyme paraoxonase-2 (PON2), whose involvement was recently reported in relation to many neoplasms." (PMID 36613780, 2022). "Among these altered genes, some oncogenes, such as PON2 and CD34, were downregulated, and some tumor suppressors, such as KLF6 and JUN were upregulated." (PMID 31723124, 2019). "A tumor subtype and stage-specific analysis revealed that both PON2 and PON3 are upregulated rather in the early stages and some subtypes of cancer, whereas the expression in the late stages of the tumor seems to be declining." (PMID 22666600, 2012). "In a study of squamous cell carcinoma (including HNSCC), elevated PON2 expression was observed in tumor tissues, correlating with malignancy grade but not with patient age, sex, or tumor differentiation." (PMID 40864763, 2025). "Western blot and immunohistochemistry analyses carried out in two separate groups of tumor and adjacent normal tissue samples obtained from cohorts of patients with oral squamous cell carcinoma (OSCC) revealed markedly increased PON2 levels in cancer compared with healthy-looking oral mucosa." (PMID 38397445, 2024). "A similar pattern was discovered in mice lacking PON2 expression, in that the rate of tumor progression was unaffected by the PON2 status of grafted LLC cells." (PMID 37337025, 2023). "An important aspect of this study was to examine the functional characteristics of macrophages and MDSCs present in the tumor microenvironment (TME) of mice with or without PON2 expression." (PMID 37337025, 2023). "The evaluation of tumor burden for male and female mice with or without PON2 expression demonstrated that PON2 expression failed to influence the initiation and progression of oncogenic Kras-driven lung tumors." (PMID 37337025, 2023). "Interestingly, stem-like tumor cells demonstrated overexpression of OXR1 and PON2, both involved in protection against ROS accumulating as co-product of OXPHOS." (PMID 33806447, 2021). "The authors suggested PON2 as a new modulator of glucose transport and pharmacologically tractable pathways necessary for tumor growth and metastasis of PDAC, and thus a novel target to attenuate tumor growth and metastasis." (PMID 33198082, 2020). "Besides the transcriptional regulation, it has been shown that Paraoxonase 2 (PON2) directly interacts with GLUT-1 to stimulate glucose uptake and therefore promote PDAC tumor growth." (PMID 31569510, 2019). "In recent years, overexpression of PON2 and PON3 has been observed in cancer cells and it has been proposed that both enzymes may be involved in tumor survival and resistance to stress." (PMID 31052559, 2019).
tumor (continued). "Consistent with the results of Real-Time PCR, lanes loaded with equal protein amounts showed markedly increased PON2 expression in tumor samples compared to that in matched normal tissues, which in some specimens showed a faintly detectable band." (PMID 28430636, 2017). "This study also shows that endogenous PON2 is essential for C12‘s cytotoxicity in human lung tumor cells and inhibitory effects on tumor growth, consistent with our previous observation of PON2 overexpression in nontransformed fibroblasts and HEK293T cells." (PMID 26758417, 2016). "Overall, our results demonstrate that C12 inhibits tumor growth independent of both pro- and anti-apoptotic Bcl-2 proteins, and through inducing unique apoptotic signaling mediated by PON2 in tumor cells." (PMID 26758417, 2016). "Furthermore, opposite to conventional chemotherapeutics, C12 requires paraoxonase 2 (PON2) to exert its cytotoxicity on tumor cells in vitro and its inhibitory effects on tumor growth in vivo." (PMID 26758417, 2016). "C12 inhibited the tumor growth through inducing apoptosis in a PON2-dependent but not Bcl-2 protein-dependent manner." (PMID 26758417, 2016). "Therefore, developing selective inhibitors or modulators that target tumour-specific PON2 overexpression without affecting normal tissue function is crucial." (PMID 40794328, 2025). "To this purpose, we conducted studies in a subcutaneous allograft lung tumor model in which LLC cells with or without PON2 expression were subcutaneously implanted in the rear flanks of wild-type and PON2-KO mice of both sexes, and subcutaneous tumor volume was measured over 24 days." (PMID 37337025, 2023). "The overexpression of PON2 in T24 cells treated with CSE phytochemicals might be related to the increase of intracellular ROS, and could represent a mechanism used by tumor cells to protect themselves from the apoptotic process induced by glucosinolates and polyphenols." (PMID 36235028, 2022). "However, to date, no data were available concerning PON2 dysregulation in OSCC (tumor versus normal oral mucosa), as well as its potential involvement in other aspects related to cancer cell phenotype, such as response to chemotherapy." (PMID 36613780, 2022). "At the same time, the studies showed the increased PON2 expression in non-melanoma skin cancers in basal cell carcinoma cells, which had a positive correlation with metastasis to lymph nodes, parameters, and the pathological stage of the tumor." (PMID 34885171, 2021). "A recent study also shows that endogenous PON2 is essential for C12 cytotoxicity (12.5, 50, and 100 μM) in human lung tumor cells and an inhibitory effect on tumor growth, consistent with the previous observation of PON2 overexpression in non-transformed fibroblasts and HEK293T cells." (PMID 33562328, 2021). "However, PON2 protein expression has not been examined at various stages of tumor development." (PMID 29531225, 2018). "Collectively, these findings suggest that in OSCC patients, low PON2 tumor levels predict absence of relapses, whereas higher PON2 levels correlate with elevated β-catenin expression, at least in the majority of cases, and may predict relapse occurrence even after accompanying irradiation therapy." (PMID 27322774, 2016).